IGF1 (insulin like growth factor 1)
Diseases named in the same sentence as IGF1 in open-access papers (continued):
Sharing a sentence is not in itself a finding about the gene and the disease.
Rett syndrome (continued). "With the exception of the studies of IGF-1 in ANS dysfunction in Rett syndrome with epilepsy, the potential role of BDNF and IGF-1 in regulating ANS function and cerebral autoregulation in patients with epilepsy has not been reported." (PMID 30524358, 2018). "The present report adds significant preliminary evidence for the use of IGF-1 in the treatment of Rett Syndrome and other disorders of the autism spectrum." (PMID 26925263, 2016). "Clinical pilot studies and early reports have supported the safety/preliminary efficacy of IGF-1 and related compounds in the treatment of Rett Syndrome, with evidence mounting for its use in Phelan McDermid Syndrome and Fragile X Syndrome." (PMID 27746717, 2016). "Stimulation of excitatory synapses and neuronal density has been achieved with insulin-like growth factor 1 (IGF-1) administration and it has been positively tested in two single gene disorders associated with ASD, Rett syndrome, and Phelan-McDermid syndrome." (PMID 25853112, 2015). "IGF1 is currently being tested in phase 2 clinical trials for Rett syndrome treatment (clinicaltrials.gov identifier: NCT01777542)." (PMID 26092527, 2015). "Fourth, there is now additional independent clinical evidence of the efficacy of IGF-1 in Rett syndrome to generate interest in this compound." (PMID 25685306, 2014). "The recent IGF-1 study in Rett syndrome examined its pharmacokinetic profile in human subjects and found that IGF-1 reached the CNS compartment as demonstrated by significantly increased cerebrospinal fluid levels after treatment." (PMID 25685306, 2014). "Recent evidence also provides preliminary support of efficacy with IGF-1 in children with Rett syndrome." (PMID 25685306, 2014). "In the case of IGF1, this feature has already been used therapeutically in preclinical settings, where the application of recombinant IGF1 was demonstrated to improve synaptic maturation in a mouse model for Rett syndrome, a type of ASD." (PMID 23346059, 2012). "Recently, a study of IGF-1 as therapeutic agent in Rett syndrome have been initiated in Children's hospital, Boston (Khwaja, Clinical Trials.Gov ID NCT01253317)." (PMID 22778966, 2012). "Systemic IGF-1 treatment of juvenile mice prevents many of the Rett syndrome symptoms, including shortened lifespan, locomotion and respiration, decreased brain weight, decreased cortical spine density, and abnormal ocular dominance plasticity." (PMID 21826280, 2011). "IGF-1 analogs, such Trofinetide, were tested in clinical trials for the treatment of Rett Syndrome." (PMID 40434434, 2025). "As IGFBP3 binds IGF-1 and IGF-1 mimetics have shown therapeutic benefits in Rett syndrome, targeting the IGF system may be a potential strategy for Rett syndrome (see Section 5.4)." (PMID 40943197, 2025). "Moreover, a pilot open-label trial with mecasermin (recombinant human IGF-1) in Rett syndrome demonstrated that the ADAMS Social Avoidance subscale’s was mildly sensitive to response to treatment." (PMID 28616097, 2017). "IGF-1 is currently an attractive compound for the treatment of Rett syndrome." (PMID 27781091, 2016). "The adverse effects could be rescued by IGF-1 supplementation which underpins the ongoing IGF-1-based clinical trials in the treatment of Rett syndrome." (PMID 26839567, 2016). "iPSCs have revealed clues about pathology and potential treatments: for example, iPSC-derived neurons from Rett syndrome patients show reduced synaptic puncta and decreased glutamatergic signalling, deficits rescued by insulin-like growth factor 1 (IGF1) application." (PMID 26092527, 2015).
Rett syndrome (continued). "Importantly, the first evidence of the efficacy of IGF-1 in an ASD-related syndrome has already emerged in Rett syndrome." (PMID 25685306, 2014). "A recent study implicates a role of miRNA in Rett syndrome through regulation of IGF-1." (PMID 25628647, 2014). "Clinical trials of recombinant human IGF-1 for Rett syndrome have reported to be safe." (PMID 25628647, 2014). "In fact, given the positive effects of IGF-1 in Rett syndrome models it is likely that IGF-1 has a general effect on CNS function, which might also be observed in controls." (PMID 23621888, 2013). "We do hope, however, that our findings, together with those on IGF-1 in Rett syndrome models, may help spur further research on the action of IGF-1 in the CNS." (PMID 23621888, 2013). "Studies in mouse and human neuronal models of Rett syndrome also show benefits with IGF-1, raising the possibility that this compound may have benefits broadly in ASD and related conditions, even with differing molecular etiology." (PMID 23621888, 2013). "Additionally, we included IGF1, which has shown its therapeutic effects for Rett syndrome." (PMID 40457513, 2025). "Importantly, IGF-1 is also effective in reversing phenotypic changes in human neuronal models of Rett syndrome, providing additional evidence that this pathway may be a target in diverse forms of ASD." (PMID 25685306, 2014). "The beneficial effects of IGF-1 in models of Rett syndrome are consistent with this hypothesis." (PMID 23621888, 2013). "Five controlled clinical studies have evaluated human recombinant IGF-1 (rhIGF-1) as a treatment of ALS and Rett syndrome." (PMID 37621718, 2023). "Experiments in a mouse model of Rett syndrome identified therapeutic potential in an FDA-approved drug, Insulin-like growth factor 1 (IGF-1)." (PMID 21826280, 2011). "Although the first disease-modifying treatment Trofinetide, a synthetic analog of glycine–proline–glutamate, the N-terminal tripeptide of the insulin-like growth factor 1 protein [IGF1], was approved by the FDA recently, treatment of Rett syndrome have been mainly symptomatic." (PMID 40596833, 2025). "Insulin-like growth factors (IGFs), particularly IGF-1, play key roles in neuronal differentiation, myelination, and synapse formation; reduced IGF-1 has been described in Rett syndrome, Fragile X syndrome, and subsets of ASD, prompting clinical trials of IGF-1 analogs." (PMID 40943255, 2025). "Indeed, trofinetide (DAYBUETM), an oral small molecule synthetic analog of an N-terminal tripeptide derivative of IGF-1, has been approved by the US Food and Drug Administration (FDA) as the first drug for the treatment of Rett syndrome (RTT) to improve social communication." (PMID 39188438, 2024).
chronic kidney disease (45 papers, 2007 to 2025). Impairment of the renal function secondary to chronic kidney damage persisting for three or more months. "For example, in a cross-sectional study of 5388 US adults, the magnitude of the (positive) association between high IGF1 levels and the risk of chronic kidney disease was found to be stronger for males than for females." (PMID 31973007, 2020). "IGF-1 is a regulator of erythropoiesis in children with short stature, adults with GH deficiency, and those affected by chronic kidney diseases." (PMID 26779261, 2015). "The A-rs35767 risk allele was previously seen to be associated with a faster decrease of glomerular filtration rate and an increase in circulating level of IGF1, which in turn was found associated with a major risk of developing DN and chronic kidney diseases in general." (PMID 37338602, 2023). "Chronic kidney disease (CKD) and its complications in children are associated with alterations in the GH/IGF1 axis, including growth retardation, related to a GH-resistant state, attributed to impaired kidney postreceptor GH-signaling and chronic inflammation." (PMID 34943879, 2021). "Chronic renal failure rats exhibit post-receptor defects in IGF-1 signaling within skeletal muscle, leading to impaired protein synthesis and increased degradation." (PMID 41262737, 2025). "Examples of such diseases are cystic fibrosis or chronic kidney disease, whereby affected children develop low insulin-like growth factor-1 concentrations or delayed puberty due chronical illness." (PMID 36900289, 2023). "The aim of the study was to evaluate circulating insulin‐like growth factor 1 (IGF‐1) in non‐diabetic cats with chronic kidney disease (CKD) and to screen this population for the presence of HST." (PMID 38053473, 2023). "Serum IGF-1 is a nutritional status marker in patients with end-stage renal disease (ESRD) and is negatively correlated with the subjective global assessment (SGA) nutritional status in patients undergoing hemodialysis." (PMID 37403637, 2023). "IGF-1 is a kind of protein that promotes anabolism, and its inhibition plays an important role in muscle atrophy in end stage renal disease (ESRD)." (PMID 33986663, 2021). "Further, decreased IGF-1 levels have been reported in diabetic, end-stage renal disease and hemodialysis patients." (PMID 27138941, 2016). "The serum IGF-1 is lower in children with chronic kidney disease (CKD) than in those with a normal GFR." (PMID 27138941, 2016). "In mice with chronic kidney disease-associated anemia, combined subtherapeutic doses of EPO and IGF-1 had a comparable effect to a single therapeutic dose of EPO on Hb concentrations." (PMID 26779261, 2015). "A high normal calculated GH secretion rate and amplified number of GH secretory bursts have been reported in pre-pubertal children with end-stage renal disease, likely due to attenuated IGF-1 feedback." (PMID 17676425, 2008). "In end-stage renal disease IGF-1 level is normal or decreased and levels of IGF binding proteins (IGFBP) are increased, thus resulting in a net decrease in IGF bioactivity." (PMID 17676425, 2008). "Chronic kidney disease (CKD) in children is associated with dramatic changes in the growth hormone (GH) and insulin-like growth factor (IGF-1) axis, resulting in growth retardation." (PMID 17676425, 2008). "Moreover, multivariate analysis including age, sex, BMI, chronic kidney disease, BNP and insulin use (Model 2) revealed that an elevated IGF-1/IGFBP-3 ratio was associated with a significantly decreased risk for CV death and 3P-MACE." (PMID 35332212, 2022). "Specific overexpression of IGF-1 in skeletal muscle attenuated the effects of angiotensin II and it was concluded that downregulation of IGF-1 may be the primary cause of muscle wasting in congestive heart failure and chronic kidney disease." (PMID 28688452, 2017). "The role of IGF-1 in adult and older people affected by anemia of chronic kidney disease (CKD) has been also studied." (PMID 26779261, 2015).
chronic kidney disease (continued). "In studies of children with chronic kidney disease, GHT led to an increase in BMD in parallel with an increase in muscle mass, primarily by increasing serum IGF-1 levels." (PMID 38610974, 2024). "Studies have shown that patients with chronic kidney disease (CKD) and anemia have lower serum IGF-1 levels." (PMID 37403637, 2023). "On the contrary, PTH, PTH-rP, angiotensin-II, IGF-1, PGE2, vitamin D, and chronic renal failure decrease its expression." (PMID 34441291, 2021). "In particular, IGF-1 seems to play an important role in the regulation of erythropoiesis in patients with end-stage renal disease and erythrocytosis without an increased EPO production." (PMID 26779261, 2015).
glioblastoma (45 papers, 2010 to 2025). The most malignant astrocytic tumor (WHO grade IV). "This targeted delivery resulted in 22-fold increase in miRNA-603 levels in glioblastoma, with a transient decrease in the expression level of insulin-like growth factor 1 and its receptor (IGFR1)." (PMID 39457052, 2024). "miRNA-603 is a regulatory RNA involved in the suppression of radiation resistance in glioblastoma via the downregulation of IGF1 signaling." (PMID 39457052, 2024). "The miR-603 was used to downregulate insulin-like growth factor 1 signaling by suppressing the glioblastoma multiforme radiation resistance." (PMID 35456655, 2022). "In one study, IGF-1 and insulin stimulated the growth of glioblastoma cells at 0.7 nmol/L and 80 pmol/L, respectively, which is well within the concentration ranges found in glioblastoma cyst fluid in the present study." (PMID 35659255, 2022). "miRNA 603 (miR-603) is a master regulatory miRNA that suppresses glioblastoma radiation resistance through down-regulation of insulin-like growth factor 1 (IGF1) signaling." (PMID 34452076, 2021). "Statistical models incorporating both high-IGF-1 and low-miR-181d statuses better predicted poor patient survival, and can be used as an independent prognostic factor in glioblastomas." (PMID 28389653, 2017). "The insulin-like growth factor (IGF)-1 signaling is relevant in regulating cell growth and cytokine secretions by glioblastomas." (PMID 28389653, 2017). "Under treatment with WP1193 in combination with IL-6 they observed increased Insulin-like growth factor I (IGF1) signaling in both normoxic and hypoxic cells which confirmed the modulatory role of IGF1 in glioblastoma proliferation and migration." (PMID 28356110, 2017). "We observed different expression level of SDF-1, RANTES, IL-6 and IL-8 in medulloblastoma-BTICs, SDF-1, RANTES, IL-6 and IL-8 in AT/RT-BTICs and SDF-1, IL-6, IL-8 and IGF-1 in glioblastoma-BTICs." (PMID 26076490, 2015). "For this reason, its silencing in glioblastoma cells causes a downregulation of genes related to tumor progression and DNA repair mechanisms, including PI3K/AKT, Insulin-like Growth Factor 1(IGF1), Fms-like Tyrosine kinase 3 (FLT3), Platelet-Derived Growth Factor (PDGF), and MAPK." (PMID 39769286, 2024). "In addition, an association of HIF-1α with TLR9 expression has been established in which HIF-1α siRNA decreases TLR9 transcripts in glioblastoma multiforme (GBM) cells treated with insulin-like growth factor 1 (IGF-1) under normoxic conditions." (PMID 38069210, 2023). "Taken together, comprehensively investigating IGF-1-mediated gene networks may be helpful in understanding the progression of gliomagenesis and provide innovative therapeutic strategies for glioblastomas." (PMID 31805126, 2019). "Our aim was to validate the IGF-1-mediated mRNA/miRNA regulatory network in glioblastomas." (PMID 28389653, 2017). "However, relationships between IGF-1 signaling and miRNAs in glioblastoma pathogenesis are still unclear." (PMID 28389653, 2017). "IGF-1 was increased only in glioblastoma-BTICs co-cultured with hAT-MSCs." (PMID 26076490, 2015). "Co-culture of BTICs and hAT-MSCs showed different expression levels of several cyto-chemokines compared with co-culture of BTICs and HFF1: SDF-1, RANTES, IL-6 and IL-8 in medulloblastoma-BTICs, SDF-1, RANTES, IL-6 and IL-8 in AT/RT-BTICs and SDF-1, IL-6, IL-8 and IGF-1 in glioblastoma-BTICs." (PMID 26076490, 2015). "Moreover, miR-153 suppresses the AKT signaling pathway in glioblastoma through reduction in expression of insulin receptor substrate-2 (Irs-2) which acts as a molecular adaptor, mediating influences of insulin and insulin-like growth factor 1 (IGF-1) on cell proliferation." (PMID 36158686, 2022). "Matrine can effectively inhibit the growth of glioblastoma multiforme (GBM) cells in vitro by inducing cell senescence, and downregulate the expression of insulin-like growth factor (IGF1), PI3K, and p-AKT." (PMID 32477114, 2020).
glioblastoma (continued). "Interestingly, IGF-1 was elevated only in glioblastoma-BTICs." (PMID 26076490, 2015). "Insulin-like growth factor-1 (IGF-1) was able to induce EMT in brain cancer cells, which contributes to the proliferation and migration of glioblastoma multiforme, a kind of aggressive brain tumor." (PMID 37446730, 2023). "In glioblastoma multiforme, IGF1/IGF1R signaling promoted survival and suppressed apoptosis of glioblastoma cells through the PI3K/AKT pathway." (PMID 32851683, 2020). "In glioblastoma, PDGFR, NGF, IGF-1 and, most essentially EGFR upregulation, mediates the migration of glioblastoma cells into normal brain tissues." (PMID 32276377, 2020). "GH and IGF-1 have been separately shown to induce EMT in various types of cancers both in vitro and in vivo, including breast, lung, colon, and glioblastoma." (PMID 33291663, 2020). "Different types of cyto-chemokines are involved in the crosstalk between hAT-MSCs and BTICs (medulloblastoma and AT/RT: CXCR4/SDF-1, CCR5/RANTES, IL6R/IL-6 and IL8R/IL8; glioblastoma: CXCR4/SDF-1, IL6R/IL-6, IL8R/IL-8 and IGF1R/IGF-1)." (PMID 26076490, 2015). "Despite promising preclinical results, CSF-1R inhibitors have shown limited efficacy in clinical trials for glioblastoma as in fact resistance to CSF-1R blockade is often observed, driven by compensatory mechanisms within the TME, including increased insulin-like growth factor-1 (IGF-1) signaling." (PMID 39457693, 2024). "miR-603 has been previously identified as a miRNA that could target both IGF1 and IGFR1 to suppress the IGF1/AKT pathway and glioblastoma stemness." (PMID 36674525, 2023). "Likewise, IGF-1, IGFBP2, SPARCL1, kininogen-1, osteopontin, and GRP78 are known to be secreted by glioblastoma cells." (PMID 35659255, 2022). "Specifically, they found that an IGF1/IGF1R inhibitor targeting YTHDF2-expressing cells could suppress GSC viability and the growth of glioblastoma in vivo in an m6A-dependent manner." (PMID 34381710, 2021). "Also, elevated IGF-1/IGF-1R signaling could inhibit the apoptosis of different cells, such as glioblastoma cells and renal carcinoma cells." (PMID 33867995, 2021). "Further, in CSCs isolated from breast and lung carcinomas, or glioblastoma (GBM), metformin-dependent cell proliferation arrest does not involve AMPK, but rather the down-regulation of IGF-1 signaling or inhibition of Akt." (PMID 25361004, 2014). "Restoration of wild-type PTEN to glioblastoma cell lines lacking functional PTEN ablates hypoxia and IGF-1 induction of HIF-1-regulated genes." (PMID 22623890, 2012). "However, inhibiting PLCγ disrupts the invasion of glioblastoma cells into normal brain tissues, regardless of the combined signaling effects of PDGFR, NGF, IGF-1, and EGFR upregulation." (PMID 32276377, 2020).